HPCAL4 (hippocalcin like 4)
Description:
May be involved in the calcium-dependent regulation of rhodopsin phosphorylation.
Synonyms: HLP4; DKFZp761G122
Tractability: PROTAC: its protein half-life has been measured.
Gene: Protein-coding gene on chromosome 1 (39,678,648 to 39,691,485, reverse strand). Ensembl gene ENSG00000116983.
Subcellular location (Human Protein Atlas): Cytosol
Gene Ontology:
Molecular function: protein binding; calcium ion binding; calcium channel regulator activity; protein domain specific binding
Biological process: central nervous system development; regulation of signal transduction
Genetic constraint (gnomAD): Loss-of-function variants: 16 observed, 18.91 expected, observed/expected ratio (o/e) 0.85, 90% interval 0.57 to 1.28. The upper end of that interval is the gene's LOEUF score, 1.28, which puts it in group 5 of 6, group 1 being the genes least tolerant of losing a copy. Missense variants: 214 observed, 270.47 expected, observed/expected ratio (o/e) 0.79, 90% interval 0.71 to 0.89. Synonymous variants: 80 observed, 104.3 expected, observed/expected ratio (o/e) 0.77, 90% interval 0.64 to 0.92.
Homologues: Orthologues: chimpanzee HPCAL4 (100% identical), dog HPCAL4 (100% identical), guinea pig HPCAL4 (100% identical), macaque HPCAL4 (100% identical), pig HPCAL4 (100% identical), mouse Hpcal4 (99% identical), rabbit HPCAL4 (99% identical), rat Hpcal4 (99% identical), tropical clawed frog hpcal4 (95% identical), zebrafish hpcal4 (90% identical), Caenorhabditis elegans ncs-2 (47% identical), zebrafish rcvrna (43% identical), and 13 more. Paralogues in human: VSNL1 (90% identical), HPCA (68% identical), HPCAL1 (67% identical), NCALD (65% identical), NCS1 (55% identical), RCVRN (46% identical), KCNIP2 (43% identical), KCNIP1 (41% identical), GUCA1B (40% identical), KCNIP4 (40% identical), GUCA1A (38% identical), KCNIP3 (37% identical), and 2 more.
Diseases named in the same sentence as HPCAL4 in open-access papers:
HPCAL4 is named in the same sentence as 8 diseases in open-access papers, as found by Europe PMC text mining. Sharing a sentence is not in itself a finding about the gene and the disease. The quoted sentences say what the papers report.
glioblastoma (2 papers, 2022 to 2024). The most malignant astrocytic tumor (WHO grade IV). "The HPCAL4 gene, which functions as a neural calcium sensor, has been recognized as a key molecule in glioblastoma." (PMID 38584840, 2024).
glioma (1 paper, 2024). A benign or malignant brain and spinal cord tumor that arises from glial cells (astrocytes, oligodendrocytes, ependymal cells). "Moreover, HPCAL4 is involved in the organization and maintenance of extracellular matrix, an essential component of the tumor microenvironment that plays a crucial role in tumor growth, infiltration and metastasis, including glioma." (PMID 38584840, 2024).
myositis (1 paper, 2018). "PI4KAP1 was found to have a higher expression in CD4+ T cells of HLA-DRB1*03-positive patients with myositis, and TRGC2, CTSW, HPCAL4, ZNF683, and GOLGA8B were found to have a higher expression in CD4+ T cells of HLA-DRB1*03-negative patients with myositis." (PMID 30157932, 2018). "We found that PI4KAP1 had a higher expression in CD4+ T cells of HLA-DRB1*03-positive myositis and that TRGC2, CTSW, HPCAL4, ZNF683, and GOLGA8B had a higher expression in CD4+ T cells of HLA-DRB1*03-negative myositis patients." (PMID 30157932, 2018).
peripheral nerve injury (1 paper, 2020). Injury to a peripheral nerve. "Taken together, these behavioral analyses indicate that Hpcal4 activity is not required for the development or maintenance of inflammation- or peripheral nerve injury-induced mechanical hypersensitivity." (PMID 32015563, 2020).
cancer (2 papers, 2013 to 2020). A tumor composed of atypical neoplastic, often pleomorphic cells that invade other tissues. "Hpcal4 belongs to the superfamily of calcium binding proteins, dysregulation of the activity of which negatively affects a wide variety of cellular processes, from homeostasis to learning and memory, to cancer and pain." (PMID 32015563, 2020). "We discovered the greatest nicotine stress response by HPCAL4 (up-regulated by 4.71 fold) and NPAS3 (down-regulated by -2.73 fold); both are genes that have not been previously implicated in nicotine exposure but are linked to cancer." (PMID 23825647, 2013).
HPCAL4 also shares sentences with these, for which no sentence is quoted: astrocytoma (1 paper); cognitive decline (1); tumor (1).